BCL9 (BCL9 transcription coactivator)
Diseases named in the same sentence as BCL9 in open-access papers (continued):
Sharing a sentence is not in itself a finding about the gene and the disease.
cholangiocarcinoma (2 papers, 2020). A carcinoma that arises from the intrahepatic biliary tree (intrahepatic cholangiocarcinoma) or from the junction, or adjacent to the junction, of the right and left hepatic ducts (hilar cholangiocarcinoma). "Most importantly, these data may have relevance to other cancers that show similar aberrant expression of BCL9 such as bladder, lung, liver, cholangiocarcinoma, and ovarian cancers." (PMID 32352029, 2020).
colitis (2 papers, 2019). Inflammation of the colon. "Given that BCL9/9l are implicated in Wnt signalling and are required for colonic regeneration following acute colitis, we sought to determine whether Wnt signalling is perturbed in BCL9/9l-deficient intestines." (PMID 30760720, 2019). "As previous studies investigating BCL9 and BCL9l (BCL9/9l) were performed in colitis-associated cancer models, we wished to investigate the effect in models of cancer directly driven by activation of Wnt signalling either by Apc gene deletion or β-catenin stabilisation." (PMID 30760720, 2019).
colorectal tumors (2 papers, 2008 to 2015). "Indeed, overexpression of B9L and BCL9 may contribute to, or even confer, persistent pathway activity that is independent of Wnt ligand, for example in colorectal tumours whose progression may thus be promoted by these proteins." (PMID 18627596, 2008).
endometriosis (2 papers, 2022 to 2024). The growth of functional endometrial tissue in anatomic sites outside the uterine body. "Increased endometrial BCL6 and BCL9 levels are considered to be a non-invasive diagnostic marker for endometriosis." (PMID 39684461, 2024). "The key oncogenes B-cell lymphoma 6 (BCL6) and BCL9 may play a role in endometriosis as well as in the placenta, another tissue type characterized by invasion and proliferation." (PMID 39684461, 2024).
liver cancer (2 papers, 2017 to 2020). An epithelial or non-epithelial malignant neoplasm that arises from the liver. "To evaluate the role of BCL9 in human HCC, we used gain-of-function and loss-of-function approaches to evaluate the function of BCL9 in human liver cancer cell lines." (PMID 28074862, 2017). "These in vitro results are in good agreement with our analysis of the TCGA liver cancer data set, showing that high BCL9 expression correlates with poor survival only in Wnt-inactive human HCCs but not in Wnt-active HCCs." (PMID 31440992, 2020). "The hitherto existing results on BCL9’s influence on liver cancer cells are not in line with our observations." (PMID 31440992, 2020). "Our results confirm Wnt responsiveness of AXIN2, while BCL9 and BCL9L seem not to be Wnt-responsive in liver cancer cells." (PMID 31440992, 2020).
lymph node metastasis (2 papers, 2017 to 2019). "We found that the level of BCL9 expression, Federation International of Gynecology and Obstetrics (FIGO) stage, and lymph node metastasis were associated with progression-free survival (PFS) and overall survival (OS) in patients, based on the log-rank test." (PMID 31827404, 2019). "BCL-9 expression was associated with AJCC TNM stage (p = 0.000), invasive depth (p = 0.000) and lymph node metastasis (p = 0.000)." (PMID 27121066, 2017).
lymphoma (2 papers, 2019 to 2021). A malignant (clonal) proliferation of B- lymphocytes or T- lymphocytes which involves the lymph nodes, bone marrow and/or extranodal sites. "BCL9 (B Cell CLL/Lymphoma 9) has significant self-correlation in 21 datasets." (PMID 31335867, 2019).
mental disorder (2 papers, 2013 to 2022). A disease that has its basis in the disruption of mental process. "One previous study reported that the BCL9 protein is required for efficient T-cell factor–mediated transcription in the Wnt signaling pathway, which has been suggested to be involved in the pathophysiology of mental disorders using animal studies." (PMID 23382809, 2013).
microcephaly (2 papers, 2012 to 2023). A congenital or acquired developmental disorder in which the circumference of the head is smaller than normal for the person's age and sex. "In agreement with this, microcephaly was noted in BCL9 deletion patients, while macrocephaly was reported BCL9 duplication patients." (PMID 23083465, 2012). "BCL9, FMO5, and GPR89B deletions related to microcephaly are also overrepresented in DD." (PMID 37486921, 2023).
pancreatic cancer (2 papers, 2016). "In 42 primary pancreatic tumors the RNA-expression of the FLI1 targets DKK1, INPP5D, IGFBP3 and additionally two members of the Wnt/β-catenin pathway, namely BCL9 and BCL9L, was investigated using quantitative real time PCR." (PMID 27539223, 2016). "Analysis of a panel of pancreatic cancer cell lines shows a consistently higher expression of BCL9L in comparison to non-cancer cell lines and compared to its homologue BCL9 (data not shown)." (PMID 27713160, 2016).
renal carcinoma (2 papers, 2022 to 2025). A carcinoma arising from the epithelium of the renal parenchyma or the renal pelvis. "Given that TPX2 has already been established as a clinically relevant factor in renal cancer, further validation would be particularly valuable for BCL9, which emerges as a potential target for enhancing tumor sensitivity to anti-PD-1/L1 therapy." (PMID 40362354, 2025). "The only study to date conducted in renal cancer identified BCL9 as a direct target of microRNA-218 (miR-218)." (PMID 40362354, 2025). "Additionally, further research is needed to investigate the interplay between TPX2 and BCL9 in renal cancer progression, particularly in the context of their role in modulating the tumor immune microenvironment." (PMID 40362354, 2025).
alcohol abuse (1 paper, 2020). The use of alcoholic beverages to excess, either on individual occasions ("binge drinking") or as a regular practice. "While expression of BCL9 seemed to be independent of tumor etiology, BCL9L levels were lowest in patients with alcohol abuse and hepatitis B infections." (PMID 31440992, 2020).
autism (1 paper, 2013). Persistent deficits in social interaction and communication and interaction as well as a markedly restricted repertoire of activity and interest as well as repetitive patterns of behavior. "The BCL9 gene resides within a ∼1.5–Mb genomic region of the 1q21.1 locus in which both deletions and duplications can result in syndromes associated with numerous phenotypes, including autism." (PMID 23825557, 2013).
Burkitt lymphoma (1 paper, 2022). A rare form of malignant mature B-cell non-Hodgkin lymphoma. "An identical translocation involving BCL9 has been previously reported in Burkitt lymphoma." (PMID 36232559, 2022).
glioblastoma (1 paper, 2022). The most malignant astrocytic tumor (WHO grade IV). "For instance, endothelial miR-30c repressed survival of tumors by inhibiting TGF-beta-induced Serpine1, while it attenuated growth of colorectal carcinoma tumors by directly targeting BCL9, and it reduced proliferation and migration of glioblastoma cells by directly targeting SOX9." (PMID 35212616, 2022).
liver failure (1 paper, 2019). A liver disease characterized by the liver losing or has lost all of its function. "AAV8-TBG-Cre Ctnnb1ex3/+ mice develop hepatomegaly within 2 weeks post-induction, and develop a liver failure phenotype which was completely suppressed through deletion of Bcl9/9l, where mice were aged up to 140 days before being euthanised." (PMID 30760720, 2019).
lobular carcinomas (1 paper, 2021). "Therefore, although pathway analysis connected BCL9 and PYGO2 protein to the “beta-catenin:TCF transactivating complex,” it is possible that those proteins play a special role in beta-catenin-independent signaling pathway both in ductal and lobular carcinomas." (PMID 33808143, 2021).
ovarian epithelial tumor (1 paper, 2019). A benign, borderline, or malignant tumor that originates from the surface epithelium of the ovary. "The immunohistochemistry results showed that BCL9 was mainly located in the nucleus in ovarian epithelial tumors and partly in the cytoplasm." (PMID 31827404, 2019). "We detect the expression of BCL9 in ovarian epithelial tumor tissues and normal ovarian tissues using immunohistochemistry and analyzed the relationship between it and clinicopathological parameters and patient prognosis." (PMID 31827404, 2019). "However, the expression and mechanism of BCL9 in human ovarian epithelial tumor tissues are still unknown." (PMID 31827404, 2019).
papillary thyroid carcinoma (1 paper, 2025). "Additionally, BCL9 KD inhibits the proliferation and invasive ability of papillary thyroid carcinoma cells and was identified as a risk factor for neck lymph metastasis." (PMID 40362354, 2025).
parasitic infection (1 paper, 2020). "Genetic variants of interest identified in several immune related genes for all the antibody response and parasitic infection traits: IBDV (TOLLIP, ANGPTL5, BCL9, THEMIS2), MDV (GRM7), SG (MAP3K21), Eimeria (TOM1L1), and cestodes (TNFAIP1, ATG9A, NOS2)." (PMID 33193617, 2020).
Premature ovarian insufficiency (1 paper, 2023). Amenorrhea due to loss of ovarian function before the age of 40. "For instance, miR-122-5p, which targets BCL-9 to induce granulosa cell apoptosis, was overexpressed in premature ovarian insufficiency (POI) ovarian-derived exosomes." (PMID 38037065, 2023).
Solid Pseudopapillary Neoplasm of the Pancreas (1 paper, 2016). A low-grade malignant neoplasm that arises from the exocrine pancreas. "Eighteen cases of solid pseudopapillary neoplasms of the pancreas were evaluated for RNA expression levels of FLI1, DKK1, INPP5D (SHIP1), IGFBP3, PBK (TOPK), and BCL9 and BCL9L." (PMID 27539223, 2016).
type 2 diabetes (1 paper, 2017). "Further, variants near FAR1 (fatty acyl-CoA reductase 1) have been previously associated with bone mineral density in Hispanic children, and BCL9 has recently been identified with type 2 diabetes in aboriginal Australians." (PMID 28417008, 2017).
tumor (85 papers, 2010 to 2025). "Researchers found that CAFs with BCL9 gene loss have a pro-tumor effect, resulting in abnormal activation of the Wnt/β Catenin pathway." (PMID 40677714, 2025). "Using a similar experimental approach, the authors further demonstrated that Bcl9 inhibition disrupts macrophage polarization from M0 to M2, a process critical for tumor-associated immunosuppression." (PMID 40362354, 2025). "To investigate this, we assessed the expression of Rel, Relb and Irf1 of cDC1 in TdLNs and tumors from B16-OVA tumor-bearing Bcl9/Bcl9l deficiency mice using SCENIC analysis." (PMID 38811552, 2024). "In summary, we successfully identified the CD8+ T cells and cDC1 populations in tumors and TdLNs from B16-OVA tumor-bearing Bcl9/Bcl9l deficiency mice using scRNA-seq." (PMID 38811552, 2024). "Consistently, positive regulation of T cell proliferation in cDC1 was also upregulated in tumors of B16-OVA tumor-bearing Bcl9/Bcl9l deficiency mice, supporting that cDC1 primed CD8+ T cells." (PMID 38811552, 2024). "Consistently, the CXCL9 expression by cDC1 and CXCR3 expression by CD8+ T cells were upregulated in tumors from hsBCL9z96-treated CT26 tumor-bearing mice, as well as from MC38 tumor-bearing Bcl9/Bcl9l deficiency mice." (PMID 38811552, 2024). "As our results showed that elevated BCL9 expression is associated with diminished antigen presentation in cancers, we explored this supposition in tumor models." (PMID 38811552, 2024). "Identically, Xcl1 mRNA and XCL1 protein levels were increased markedly in these tumors using qPCR, as well as tumors from MC38 tumor-bearing Bcl9/Bcl9l deficiency mice." (PMID 38811552, 2024). "The frequency of OVA257-264-specific CD8+ T cells was increased in TILs from MC38-OVA tumor-bearing Bcl9/Bcl9l deficiency mice compared to the control." (PMID 38811552, 2024). "Increased expression of these activation markers on cDC1 was observed in this model, as well as in MC38 tumor-bearing Bcl9/Bcl9l deficiency mice." (PMID 38811552, 2024). "We analyzed transcriptional changes and signaling enrichment of cDC1 in tumors and TdLNs from B16-OVA tumor-bearing Bcl9/Bcl9l deficiency mice." (PMID 38811552, 2024). "We found that tumor growth was notably decreased in MC38 tumor-bearing Bcl9/Bcl9l deficiency mice compared with control mice, with a TGI of 65.6%." (PMID 38811552, 2024). "BCL9 is elevated in adrenal malignancies, and its upregulation level is significantly associated with tumor aggressiveness." (PMID 38269250, 2023). "The B-cell CLL/lymphoma 9 protein, encoded by BCL9, is involved in the Wnt pathway which is essential in the tumour progression process." (PMID 35328739, 2022). "This matches with other studies which found that somatic CN of BCL9 gene was associated with advanced HCC tumor stage." (PMID 34978646, 2022). "Bcl9 depletion leads to the tumor-promoting effect of cancer-associated fibroblasts (CAF), and Bcl9 depletion inhibits Wnt The abnormal activation of /β-catenin signal is conducive to the anti-tumor immune response mediated by T cells." (PMID 35836256, 2022). "Changes in the BCL9-mediated signaling pathway caused changes in the balance of cell populations in the tumor microenvironment to affect the prognosis of cancer patients." (PMID 34566638, 2021). "We applied SCENIC analysis to investigate the transcription factors underlying differences in CT26 tumor cell expression between NT and Bcl9 KD tumor cells." (PMID 34026600, 2021). "We also identified Foxp4 as a candidate transcription factor underlying gene expression differences in NT and Bcl9-KD tumor cells." (PMID 34026600, 2021). "We have found that the disruption of the interaction of β-catenin with Bcl9/Bcl9L proteins in tumor cells of MMTV-PyMT transgenic mice causes a significant reduction in primary tumor growth and metastasis formation." (PMID 34545187, 2021).
tumor (continued). "Of note, Bcl9/9l ablation in primary tumors caused a compelling shift of the tumor phenotype: the neoplastic epithelium displayed the sudden loss of traits associated with EMT and invasiveness without affecting the surrounding healthy epithelial cells." (PMID 33085215, 2021). "Our research results found that the loss of BCL9 function can make the tumor endothelial cell and fibroblast population clearly grouped." (PMID 33552975, 2020). "In this type of tumor endothelial cells and fibroblasts derived from BCL9 functional loss samples, the biological processes related to the formation of extracellular matrix have undergone significant changes." (PMID 33552975, 2020). "Through its interaction with paraspeckle proteins, BCL9 enhances the mRNA stability of neural associated genes and the release of neurotransmitters, therefore sustaining communication among tumor cells and TME remodeling." (PMID 31911584, 2020). "We also observed qualitative differences between Bcl9 and Pygo loss regarding the tumour phenotypes." (PMID 30760710, 2019). "Here we examine the requirement of BCL9/9l, constituents of the Wnt-enhanceosome, for intestinal transformation following loss of the tumour suppressor APC." (PMID 30760720, 2019). "We used two mouse tumour models based on different Apc germline mutations (ApcMin and Apc1322T) to assess the roles of the Wnt enhanceosome components Bcl9 and Pygo in intestinal neoplasia." (PMID 30760710, 2019). "We conclude that loss of Bcl9 in the intestine, despite elevating tumour numbers, slows down the growth of these tumours, suggesting a role of Bcl9 in promoting their proliferation." (PMID 30760710, 2019). "The tumours that arose were deficient for BCL9, and despite being positive for nuclear β-catenin, were also negative for Lgr5." (PMID 30760720, 2019). "To understand the relative dependencies of β-catenin mutant and APC-deficient tumours on BCL9/9l, we examined the intracellular distribution of β-catenin." (PMID 30760720, 2019). "Bcl9 loss also promotes tumour retention in ApcMin mice, apparently via relocating nuclear β-catenin to the cell surface, but this undesirable effect is not seen in Apc1322T mice whose Apc truncation retains partial function in regulating β-catenin." (PMID 30760710, 2019). "For example, we observed a strong synergy between Bcl9 loss and Pygo loss in the suppression of neoplastic disease, and in the shift of adenomatous gene expression from neoplastic towards normal, consistent with this model." (PMID 30760710, 2019). "BCL9 overexpression has been linked to increased tumor cell proliferation, survival, migration, and invasion by enhancing β-catenin-mediated transcriptional activity." (PMID 23825644, 2013). "Further research is required to determine whether BCL9-associated changes in the tumor microenvironment are relevant to ccRCC." (PMID 40362354, 2025). "Similar results were also obtained in TdLNs from MC38-OVA tumor-bearing Bcl9/Bcl9l deficiency mice." (PMID 38811552, 2024). "Furthermore, we demonstrated that TAK1/NF-κB/IRF1 signaling was also activated in cDC1 from TdLNs of MC38 tumor-bearing Bcl9/Bcl9l deficiency mice using multiplex immunofluorescence." (PMID 38811552, 2024). "To investigate this hypothesis, we used Batf3−/− mice and found that increased anti-tumor immunity upon Bcl9/Bcl9l blockade was lost in cDC1-deficiency mice." (PMID 38811552, 2024). "Similarly, increased Ifng mRNA and IFN-γ protein levels were observed in tumors from hsBCL9z96-treated CT26 tumor-bearing mice and MC38 tumor-bearing Bcl9/Bcl9l deficiency mice." (PMID 38811552, 2024). "Similarly, the expression of genes related to antigen processing and presentation such as Tap1, Tap2, B2m, and Psmb9, was also upregulated in tumors from hsBCL9z96-treated CT26 tumor-bearing mice and MC38 tumor-bearing Bcl9/Bcl9l deficiency mice." (PMID 38811552, 2024).